ACTA1 (actin alpha 1, skeletal muscle)
Diseases named in the same sentence as ACTA1 in open-access papers (continued):
Sharing a sentence is not in itself a finding about the gene and the disease.
myopathy (continued). "Structural muscle genes (ACTA1, TTN) were reduced to levels similar to those in DM, while markers of muscle regeneration (NCAM1, PAX7, MYH3, MYH8) were only mildly increased compared to normal muscle, and lower than in other inflammatory myopathies." (PMID 41441888, 2025). "Other ACTA1 missense mutations are not sequestered in the CCT complex, and a mutant protein is produced, leading to myopathy in the heterozygous state." (PMID 34600884, 2021). "Alternatively, one could speculate that the constipation and mild ventricular dysfunction seen in NAA80 individuals reflect a minor ACTG2 and ACTC1 dysfunction, in a similar way as the mild myopathy of NAA80 individuals reflects a minor form of the severe, lethal myopathy seen in ACTA1 individuals." (PMID 34805998, 2021). "Experimental trials with myostatin in two mouse models of Acta1 nemaline myopathy did not yield stronger mice, but in the TgACTA1D286G mouse model the body size increased and a similar trial in the Acta1H40Y mouse model led to both larger size and longer life-span." (PMID 31228046, 2019).
cancer (30 papers, 2014 to 2026). A tumor composed of atypical neoplastic, often pleomorphic cells that invade other tissues. "Regarding the remaining DEPs, Myh4, Acta1, Tnnt3, Mb, Ttn, Actn2, Myh7, Myl1, Mybpc2, Myl3, and Tnnc2 are associated with several cancers." (PMID 39861068, 2024). "Similarly, CapG and ACTA1, which are major components of the cell cytoskeleton, are also implicated in cancer initiation and progression and are linked to the outcome of cancer patients." (PMID 37958747, 2023). "A comprehensive RNA-Seq analysis revealed significant mRNA upregulation of several genes, including ACTA1, IGFBP2, MUC5B, CEACAM5, and KRT19, all of which are associated with cancer progression in various types of malignancies (p < 10−10)." (PMID 40004774, 2025). "For example, the linkers (MLLT4 and ACTA1) mediated the cross-talk of “Tight junction” with “Adherens junction” through regulating important cell functions in cancer, such as “cell motility/migration ”, “cell adhesion ” and “cell junction assembly ”." (PMID 25137136, 2014). "Additionally, genes like ACTA1, COL4A3, A2M, ADRB2, MYOC, among others, are closely associated with cancer biomarkers, candidate prognostic factors, and therapeutic targets." (PMID 39968416, 2025). "While skeletal α-actin gene, ACTA1, was recurrently amplified or overexpressed, its amplifications and deletions were co-regulated with MDM4 at chromosome 1q42.13 across cancers." (PMID 33217970, 2020). "Through the SAM calculation process, ACTA1, ASPN, C4orf7, CYP26B1, and PRAME showed statistically significant differences in expressions between early and late stages of cancer in both Asian and non-Asian samples." (PMID 24982892, 2014).
cardiac disease (5 papers, 2020 to 2024). "In addition, we found several upregulated genes that are implicated in cardiac disease, including bone morphogenetic protein 4 (Bmp4) (LogFC 0.728), α-actin (Acta1) (LogFC 3.335), and myosin heavy chain β (Myh7) (LogFC 1.954)." (PMID 35603785, 2022). "We observed significant upregulation of heart disease markers such as Myh7, Xirp2, and Acta1, indicating the successful establishment of the MI and TAC models." (PMID 39502510, 2024). "Some of the highest stretch up-regulated genes in our dataset are well known in cardiac disease: skeletal alpha (α)-actin, ACTA1, is involved in regulation of muscle contraction as well as cytoskeleton organization." (PMID 35805966, 2022). "Reactivation of the fetal gene program is a classic indicator of cardiac disease remodeling; hence, expression levels of five commonly measured fetal genes (Acta1, Myh6, Myh7, Nppa and Nppb) were examined via real-time quantitative PCR (qPCR) from LV tissue." (PMID 31899774, 2020). "We further examined the molecular markers for cardiac disease and fibrosis, including NPPA, NPPB, ACTA1, and FBN1." (PMID 35369338, 2022).
muscular disorder (1 paper, 2015). "The presence of nemaline rods in the skeletal muscle biopsy examined by light and electron microscopy, and ACTA1 mutation analysis (c.1127G > C) confirmed this muscular disorder." (PMID 25890230, 2015).
ACTA1 also shares sentences with these, for which no sentence is quoted: listeriosis (11 papers); Cachexia (5); lung carcinoma (5); colon carcinoma (4); atherosclerosis (3); distal myopathy (3); hepatocellular carcinoma (3); hypertrophy (3); liver fibrosis (3); melanoma (3); osteosarcoma (3); anemia (2); Arrhythmia (2); autoimmune disease (2); autoimmune hepatitis (2); brain ischemia (2); congestive heart failure (2); diabetes (2); Down syndrome (2); maturity onset diabetes (2); Myocardial fibrosis (2); myocarditis (2); neuromuscular disease (2); pulmonary arterial hypertension (2); pulmonary hypertension (2); renal fibrosis (2); sarcopenia (2); alcohol dependence (1); anxiety disorder (1); arrhythmogenic right ventricular cardiomyopathy (1).
A further 75 diseases each share a sentence with ACTA1 in 1 paper.